NLRP12 (NLR family pyrin domain containing 12)
Diseases named in the same sentence as NLRP12 in open-access papers (continued):
Sharing a sentence is not in itself a finding about the gene and the disease.
infection (continued). "We found that VSV infection downregulates NLRP12 expression, and its deletion in BMDC provokes severe transcription and production of IFN-I (IFNα/β) and TNF that corresponds with reduced viral titer and relative genomic copy in Nlrp12–/– DCs upon infection." (PMID 34768828, 2021). "Consistently, higher inflammatory responses in Nlrp12-/- mice during Salmonella Typhimurium infection helped resolve the infection." (PMID 31941025, 2020). "NLRP3 is a classic sensor and has been reported to drive GSDMD cleavage in response to pathogen infection; therefore, we investigated the roles of the newly discovered NLRs NLRP12 and NLRC4." (PMID 32295623, 2020). "Conversely, NLRP12 plays an undefined role in dampening the immune response to S. Typhimurium, and deficiency of this NLR leads to resistance to infection, independently of caspase‐1." (PMID 32185892, 2020). "There are several implications of the finding that the level of expression of NLRP3, NLRP12, and IFI16 inflammasomes is increase following infection virulent HSV-1 strains and this was associated with severe corneal inflammatory herpetic disease." (PMID 31367214, 2019). "We identified 11 genes that were significantly altered after infection with both viruses, and among these genes, 6 were up-regulated after infection (Chl1, Nlrp12, Plk1, Cyfip2, Adamts3, and Pdzk1)." (PMID 30713529, 2018). "We identified a set of 551 transcripts whose expression was modulated at least one log2-fold change in response to the infection independently of NLRP12 expression (overlapping zone in Venn diagram)." (PMID 30559449, 2018). "The expression of the pattern-recognition receptors Nlrp3, Nlrp12, and Nlrp1a was significantly increased after infection." (PMID 28604600, 2017). "In contrast, significantly fewer neutrophils were recovered from the BAL fluid following infection with F. tularensis LVS in Nlrp12−/− mice compared with WT (C57BL/6N)." (PMID 27779193, 2016). "In contrast, NLRP12 has a detrimental role in infection with S. typhimurium through negative regulation of NF-κB and MAPK11." (PMID 27779193, 2016). "The literature surrounding NLRP12 is complex as several lines of investigation suggest contradictory roles for NLRP12 in response to infection with bacterial pathogens." (PMID 27779193, 2016). "In the current study, we demonstrate a novel role for NLRP12 in host defense against infection with F. tularensis LVS, S. aureus and P. aeruginosa." (PMID 27779193, 2016). "To further characterize the role of NLRP12 in the response to F. tularensis LVS infection, we next asked what the mechanism is by which NLRP12 acts in macrophages to direct neutrophil migration." (PMID 27779193, 2016). "Analogous to the loss of neutrophils in the BAL fluid, we also observed a similar defect in the number of neutrophils recruited across the endothelial barrier into the lung parenchyma of Nlrp12−/− mice 6 days post infection with F. tularensis LVS." (PMID 27779193, 2016). "In this study, the authors showed that following infection, mice were hyper-responsive to E. coli-derived LPS in a mechanism that is dependent on NLRP12/NLRP3 inflammasome activation." (PMID 25329161, 2014). "The lungs of Nlrp12−/− and wild type mice were harvested at 1, 14, 26 and 177 days post-infection to evaluate bacterial burden and cytokines following Mtb infection." (PMID 23577168, 2013). "We found that the mean survival was 217 days post-infection for Nlrp12−/− mice and 220 days for wild type mice." (PMID 23577168, 2013). "TNFα and IL-6 levels were also comparable between the lungs of Nlrp12−/− and wild type mice at one day postinfection and during the chronic phase of the infection." (PMID 23577168, 2013).
infection (continued). "Through immunofluorescence staining of the VSV virus, we observed an intriguing phenomenon in which various‐sized round vesicular structures, seemingly indicative of the viral budding process, appeared outside the cells after infection, with NLRP12‐119aa significantly inhibiting their formation." (PMID 39754725, 2025). "Western blot results and qRT-PCR results revealed that NLRP12 expression was notably reduced in all three macrophage cell lines post-infection, indicating that NLRP12 expression is regulated upon HSV-1 infection and likely plays a role in the immune response of macrophages following HSV-1 infection." (PMID 39119293, 2024). "Now that NLRP12's regulation and function in inflammatory cell death have been identified in this study, potential therapies can be developed to target NLRP12 or molecules in its regulatory pathway to prevent cell death and inflammation in diverse infections and inflammatory diseases." (PMID 37700491, 2023). "The formation of the NLRP12‐PANoptosome in response to heme plus PAMPs or TNF suggests a critical role for NLRP12‐mediated PANoptosis in innate immune responses to conditions where free heme is released, including haemolytic diseases, infections, inflammatory conditions and some cancers." (PMID 37700491, 2023). "If one considers that most of evolution is driven by lucky side-effects, the additional targets IRF3, TAB1 and NLRP12 could give a selective advantage if their cleavage would either enhance transmission or delay the response to infection." (PMID 33372854, 2021). "While its role during infection with enteric Yersinia species in vivo is yet to be defined, mouse NLRP12, whose activation mechanisms remain poorly understood, also contributes to IL‐1β release from bone marrow‐derived macrophages infected with Y. pseudotuberculosis or Y. enterocolitica." (PMID 32185892, 2020). "However, compared to less-virulent strains, the virulent strains induced higher activation of NLRP12 at 2 h post-infection of hTCEpi cells." (PMID 31367214, 2019). "Such imbalance in the tolerogenic milieu suggested to us that C. rodentium may exploit NLRP12 signaling for limiting the accumulation of monocytes when being recruited at the site of the infection." (PMID 30559449, 2018). "To determine if the defective neutrophil recruitment observed in Nlrp12−/− mice affected their ability to control bacterial infections in vivo, analogous to the C57BL/6J mice with the missense polymorphism in Nlrp12, we utilized a pulmonary F. tularensis LVS infection model." (PMID 27779193, 2016). "Nlrp12−/− and wild type mice were infected with Mtb via aerosol infection." (PMID 23577168, 2013). "Thus, prolonged stimulation in macrophages can induce expression of the NLRP12 or pyrin inflammasomes, which could be relevant to in vivo infections where pathogens typically linger for many days." (PMID 39076995, 2024). "Interestingly, within these intersections, two genes, PHGDH and NLRP12, consistently appeared at all time points, and their expression trends remained largely consistent across various infection time points." (PMID 38257759, 2023). "However, the role of NLRP12 in the activation of the inflammasome has not been observed in diverse pathophysiological contexts, except infection caused by Yersinia pestis." (PMID 31941025, 2020). "All these cell types are exposed to infection by pathogens, but the different expression profiles of NLRP3, NLRP6, NLRP10, and NLRP12 probably reflects that each cell type has a distinct cell physiology that pathogens would evolve to target." (PMID 39076995, 2024). "In accordance with the RNA-seq and qRT-PCR data, deletion of ALKBH5 decreased NLRP12, while increased TNC protein expression in neutrophils during the early stage of infection." (PMID 35764614, 2022).
infection (continued). "To validate the cleavage of IRF3, TAB1 and NLRP12 in SARS-CoV-2 infected cells, we conducted two infection experiments in two separate laboratories to study the expression levels of these proteins." (PMID 33372854, 2021). "Firstly, NLRP12 expression was inhibited in human macrophage following DENV or other flaviviruses (JEV, YFV, ZIKV) infection." (PMID 34956178, 2021). "The relative amounts of IRF3, TAB1 and NLRP12 were quantified by densitometry and presented as a ratio of COXIV after normalization with mock infection conditions." (PMID 33372854, 2021). "Taken together, we demonstrated a novel mechanism that NLRP12 exerted anti-viral properties in DENV and other flaviviruses (JEV, YFV, ZIKV) infection, which brings up a potential target for the treatment of DENV infection." (PMID 34956178, 2021). "Cells were harvested at 2, 8, and 24 h post-infection and the level of expression of NLRP3, NLRP6, NLRP12, IFI16, and AIM2 was determined by western blot." (PMID 31367214, 2019). "Having demonstrated that infection with virulent HSV-1 strains increased NLRP3, NLRP12, and IFI16 inflammasome in infected human corneal epithelial cells, we next determined the level of expression of several components downstream of these inflammasomes." (PMID 31367214, 2019). "To determine if the defect in CXCL1 production was restricted to infection with viable bacteria, we challenged BMDM from WT (C57BL/6N) and Nlrp12−/− mice with a variety of toll-like receptor (TLR) agonists." (PMID 27779193, 2016). "Circulating neutrophils were markedly increased at day 3 post infection in both WT (C57BL/6N) and Nlrp12−/− mice." (PMID 27779193, 2016). "Understanding the individual and combined roles of NLRC3, NLRP6, NLRP12, and NLRX1 during specific infections or models of inflammation will be important as this field moves forward." (PMID 24062750, 2013). "Previous studies characterizing NLRP12 in human monocyte cell lines revealed that NLRP12 functions as a negative regulator of NF-κB signaling following stimulation with TLR agonist, TNFα and infection with M. tuberculosis." (PMID 23577168, 2013). "Furthermore, soft clustering analysis and LASSO/Cox machine learning methods were employed to successfully analyze the changes in expression profiles across various infection time points, leading to the identification of two important genes, PHGDH and NLRP12." (PMID 38257759, 2023). "Our previous studies show that infection with either P. vivax or P. falciparum prime circulating monocytes to express an inflammasome gene signature, form AIM2, NLRP3, and NLRP12 specks, express active caspase-1, and produce high levels of IL-1β, when challenged with LPS18,19,32." (PMID 32929083, 2020). "Moreover, the expression levels of NLRP3, NLRP12 and IFI-16 was sustained longer (i.e., until 24 h) in THP-1 cells after infection with the virulent strains." (PMID 31367214, 2019). "At 2 and 8 h (but not at 24 h) post-infection of hTCEpi cells, all strains, regardless of virulence, induced expression of NLRP12 at a level higher than mock." (PMID 31367214, 2019). "NLRP12-deficient mice were also more susceptible to an intraperitoneal route of infection with F. tularensis LVS compared with WT mice, suggesting that the role of NLRP12 in host defense is not restricted to the lung." (PMID 27779193, 2016). "However, the production of IL-6, TNFα and IL-10 in response to infection with F. tularensis LVS, S. aureus or P. aeruginosa was similar between WT (C57BL/6N) and Nlrp12−/− BMDM." (PMID 27779193, 2016). "Other pathogens such as Klebsiella pneumoniae and Mycobacterium tuberculosis and bacterial components such as LPS do not seem to depend on NLRP12 for infection or pathology." (PMID 24137163, 2013).
infection (continued). "For example, a recent study showed a role for NLRP12 in inflammasome formation and IL-1β/IL-18 maturation in response to a subcutaneous infection with a genetically attenuated strain of Yersinia, but not other activators that engage the NLRP3 inflammasome." (PMID 23577168, 2013). "However, the signaling pathways during infection or inflammation in vivo are not yet completely defined, and the characteristics of anti-inflammatory inflammasomes such as NLRP12 have not yet been extensively investigated." (PMID 28178176, 2017). "In contrast, NLRP12 exhibits as a negative mediator of NF-κB and MAPK signaling during infection with S. typhimurium, Klebsiella pneumoniae, Mycobacterium tuberculosis, or vesicular stomatitis virus, as well as during colon tumorigenesis." (PMID 36189207, 2022). "However, Nlrp12−/− mice failed to control replication of F. tularensis LVS, S. aureus and P. aeruginosa in vivo, a failure that correlated with a defective recruitment of neutrophils to the site of infection." (PMID 27779193, 2016).
tumor (20 papers, 2013 to 2025). "Altogether, these data demonstrate that NLRP12 deficiency promotes the activation of the Wnt/β-catenin pathway in the tumor epithelium." (PMID 37581937, 2023). "To understand the nature of inflammatory responses in the context of NLRP12-deficiency, we measured different cytokines, chemokines, and inflammatory mediators in the tumor-bearing livers from DEN or DEN plus CCl4-treated mice." (PMID 30990169, 2019). "Nlrp12 deficiency leads to higher tumor development in Apcmin/+ mice." (PMID 37581937, 2023). "Indeed, in our earlier study, we observed an increased tumor burden in bone marrow chimera mice having NLRP12 deficiency in the hematopoietic compartment." (PMID 37581937, 2023). "Inflammation is a well-known trigger for tumor growth; thus, higher inflammation and activation of inflammatory signaling pathways were considered the underlying cause of increased tumorigenesis in Nlrp12–/– mice." (PMID 37581937, 2023). "As some NLRs, like NLRP12, seem to be regulators of inflammation it could be hypothesized that mutations in these genes could correlate with tumor initiation and progression." (PMID 24273542, 2013). "However, NLRP12-deficiency significantly increased hepatocyte proliferation in tumor tissues." (PMID 30990169, 2019). "Overall, targeting NLRP12 for tumor treatment has considerable potential, but the specific mechanism of action involving NLRP12 needs to be further explored and studied." (PMID 40796546, 2025). "Compared with control treatment, NLRP12 overexpression significantly increased tumor burden parameters (size/volume/weight), whereas HK2 knockdown significantly decreased these tumorigenic metrics." (PMID 40796546, 2025). "Knockdown of NLRP12 significantly inhibited tumor size and volume in vivo, whereas the overexpression of NLRP12 increased tumor size and volume in vivo." (PMID 40796546, 2025). "The results showed that NLRP12-lentivirus promoted tumor volume and tumor weight compared with that in the Ctl-lentivirus group." (PMID 37658975, 2023). "Littermate Nlrp12–/– mice also developed higher tumor burden and invasive adenocarcinoma compared with littermate WT mice." (PMID 37581937, 2023). "As we measured β-catenin levels in isolated cells, we found higher activation of β-catenin and induction of Wnt target genes, including Ctnnb1, cMyc, and Ccnd1, in Nlrp12–/– tumor epithelial cells." (PMID 37581937, 2023). "In summary, this study mechanistically demonstrates that NLRP12 in the tumor epithelium plays a pivotal role in regulating their proliferation, invasion, and migration." (PMID 37581937, 2023). "Nlrp12-/- mice developed significantly higher tumor burden in the liver following administration of mutagens." (PMID 30990169, 2019). "Consistent with pathological features, there was significantly higher expression of cytokines IL-6 (Il6) and TNFα (Tnfa), chemokines KC (Cxcl1), MIP2 (Cxcl2), and MCP1 (Ccl2), and tumor-promoting molecule COX2 (Cox2) in Nlrp12-/- HCC." (PMID 30990169, 2019). "The correlation of tumor abundance as well as PML deficiency as well as downregulated RASSF6 and NLRP12 expression was confirmed in our patient cohort." (PMID 31144474, 2019). "This is in line with our results where NLRP12 inhibition in microglia leads to increased colony formation indicative of a tumor like phenotype." (PMID 31186453, 2019). "Nlrp12-/- mice were highly susceptible to DEN-induced HCC with increased inflammation, hepatocyte proliferation, and tumor burden." (PMID 30990169, 2019). "Nlrp12-/- tumor cells exhibited significantly increased phosphorylation of JNK, while no remarkable difference in the activation of ERK, p38, NF-κB pathways was observed." (PMID 30990169, 2019). "Tumor sizes and tumor/body weight ratios of Nlrp12-/- mice were significantly larger compared to those of WT mice." (PMID 30990169, 2019).